FSTL1 (follistatin like 1)
Diseases named in the same sentence as FSTL1 in open-access papers (continued):
Sharing a sentence is not in itself a finding about the gene and the disease.
Obesity (continued). "A recent study showed that obesity reduces circulating FSTL1 levels." (PMID 35585770, 2022). "Obesity has been reported to decrease serum FSTL1 levels in both the present and previous studies." (PMID 35585770, 2022). "Together, these results suggest that FSTL1 could be a novel pro-inflammatory adipokine mediating AT inflammation in obesity." (PMID 35909571, 2022). "Follistatin-like 1 (FSTL1), an adipokine and myokine reported as a pre-adipocyte/adipocyte-secreted protein, has a pro-inflammatory action and possible relationship with overweight and obesity." (PMID 33807959, 2021). "Considering the new data, FSTL-1 is a cardio/adipokine and then it could be a new target for therapeutic nutritional interventions for obesity and related cardiovascular diseases." (PMID 33171610, 2020). "To date, several studies have identified diverse FSTL1 functions which may play a role in obesity and support our findings." (PMID 30595761, 2018). "Therefore, FSTL1 has been linked to processes potentially relevant to the pathogenesis of the BBS phenotype, particularly obesity." (PMID 28852127, 2017). "Moreover, Fstl1 levels were reduced significantly upon induction of obesity in C57/BL6 mice fed ad libitum with a Western diet during 10 weeks." (PMID 28852127, 2017). "Furthermore, eight of the 17 CpG sites reside in genes (FSTL1, SORCS2, NRF1, DLC1, PPARGC1B, CHN2, NXPH1) that have prior known associations with obesity, diabetes, and the insulin pathway." (PMID 28068899, 2017). "As FSTL1 is a known inhibitor of Activin signaling, obesity-induced increase in FSTL1 could decrease osteogenesis, leading to weakened bones and susceptibility to fractures." (PMID 27746742, 2016). "Fractionating the adipose tissue into adipocytes and stromal vascular factions may help determine which faction contributes to the increase of FSTL1 expression in adipose tissue during obesity." (PMID 24347831, 2013). "We aimed to test whether FSTL1 could have a role in obesity-induced inflammation and insulin resistance." (PMID 24347831, 2013). "We next sought to explore the functional significance of increased FSTL1 expression in obesity." (PMID 24347831, 2013). "However, FSTL1 serum levels are found to be significantly lower in patients with severe obesity, which could be because of the reduction in adipogenesis and senescence of preadipocytes." (PMID 35909571, 2022). "Moreover, miRNAs were found to be deregulated in obesity, represented among others by downregulation of miR-206, which could further lower the impact of the evaluated SNP on final FSTL1 concentration." (PMID 30595761, 2018). "In addition, FSTL1 has also been proposed to be a regulator of inflammation and may play a role in inflammation related to obesity and insulin resistance." (PMID 28852127, 2017). "Thus, FSTL1 may provide a link between adipocytes and macrophages in adipose tissue and mediates chronic inflammation in obesity." (PMID 24347831, 2013). "In contrast, cardiac FSTL1 has the opposite effect as CTRP6, and an increase in FSTL1 promotes preadipocyte-to-adipocyte conversion and enhances adipogenesis in obesity and diabetes." (PMID 37667400, 2023). "Significantly impaired adipogenesis has been observed in obesity and diabetes, and CTRP6 and FSTL1 are involved in pathological adipogenesis." (PMID 37667400, 2023). "However, the role of FSTL1 in obesity-associated inflammation has not previously been studied." (PMID 24347831, 2013). "Although neither acute nor 7 days of mild intermittent hypoxia exposure induced changes in plasma concentrations of several myokines in people with obesity, we found that hypoxia exposure (1% O2) increased the secretion of SPARC, follistatin like 1 (FSTL1) and IL-6 in primary human myotubes." (PMID 39298040, 2025). "The obesity‐induced decrease in circulating FSTL1 levels is not explained by the skeletal muscle, myocardium or adipose FSTL1 expression." (PMID 35585770, 2022).
Obesity (continued). "Although FSTL1 expression is low in adipocytes and macrophages, it can be induced by inflammatory stimuli such as TNF-α and LPS, suggesting its potential role in mediating obesity-induced inflammation." (PMID 35909571, 2022). "Follistatin-like 1 (FSTL1) is a secreted adipomyokine with a possible link to obesity; however, its connection to extreme obesity currently remains unknown." (PMID 30595761, 2018). "Notably, FSTL1 levels were not influenced by obesity (obese: 11,045.46 ± 265.51 ng/mL vs. non-obese: 11,458.37 ± 618.22 ng/mL; p = 0.544), indicating that the associations between FSTL1 and OSA severity are obesity-independent." (PMID 41458545, 2025). "Since obesity is characterized by a whole-body low-grade inflammation state, one may not be surprised by the previously reported upregulation of FSTL1 in overweight/obese individuals." (PMID 30595761, 2018). "However, since this role of FSTL1 has not been sufficiently addressed in existing publications, we decided to address the gap in order to provide information which could be helpful in both therapy and in interventions addressing obesity." (PMID 30595761, 2018). "Furthermore, FSTL1 expression was markedly increased in adipose tissues of ob/ob mice, though this genetically obese model may not sufficiently recapitulate the features of obesity in humans." (PMID 24347831, 2013).
breast carcinoma (20 papers, 2017 to 2026). "Considering that FSTL1 is deficient in all types of human breast cancers, we regard FSTL1 as a possible human breast cancer suppressor." (PMID 37238210, 2023). "Our laboratory previously reported that FSTL1 deficiency accelerates the growth of breast cancer cells at metastatic lung sites." (PMID 37238210, 2023). "Our results showed that M2-like TAMs were significantly increased in the FSTL1-deficient lungs during breast cancer transfer." (PMID 37238210, 2023). "In contrast, in esophageal squamous cell carcinoma, gastric cancer, colorectal cancer, and breast cancer, increased expression of FSTL1 is associated with a poor prognosis." (PMID 35805015, 2022). "Collectively, these results demonstrate that FSTL1 deficiency in the microenvironment indirectly facilitated the metastatic growth of breast cancer cells in lungs." (PMID 33639614, 2021). "NRP1 has been shown to be highly expressed in different cancer types and together with FSTL1 is predicted to be driver for basal-like breast cancer by DMA." (PMID 40258059, 2025). "And there was a miR-137/FSTL1/integrinβ3/Wnt/β- Catenin signal axis maintaining stemness and enhancing chemoresistance in breast cancer cells." (PMID 37122564, 2023). "By analyzing public data, we found that FSTL1 expression was significantly low in breast cancer tissues compared to normal breast tissues, and high expression of FSTL1 in patients indicated prolonged survival." (PMID 37238210, 2023). "In the present study, we analyzed the potential function of FSTL1 in patients with breast cancer using a public database." (PMID 37238210, 2023). "To further predict the role of FSTL1 in breast cancer, we analyzed the survival rates of patients with breast cancer." (PMID 37238210, 2023). "The results showed that FSTL1 expression was significantly lower in all invasive breast cancers compared to that in normal breast tissues." (PMID 37238210, 2023). "Using flow cytometry, we found that total and M2-like macrophages dramatically increased in the metastatic lung tissues during breast cancer lung metastasis in Fstl1+/− mice." (PMID 37238210, 2023). "To investigate how 4T1 cells affect M2-like TAMs and the role of FSTL1 during breast cancer metastasis, we treated 4T1 cells with FSTL1/IL4 and detected the expression of some M2-like TAMs-associated factors using q-PCR." (PMID 37238210, 2023). "To further investigate the functional mechanism of FSTL1 in breast cancer, we established a breast cancer lung metastasis mouse model." (PMID 37238210, 2023). "To confirm the suppressive role of FSTL1 in human breast cancer, we collected invasive breast cancer samples from TCGA and sorted them into different types." (PMID 37238210, 2023). "A previous study showed that FSTL1 promoted the Wnt/β-catenin–responsive TOPflash luciferase activity in breast cancer cells and that the FSTL1-induced TOPflash activity was inhibited by integrin β3 knockdown." (PMID 35525270, 2022). "Collectively, these data demonstrate that FSTL1 deficiency in the microenvironment not only diminishes CD8+ T cells, but also inhibits the activity of Th1 cells in lung metastasis of breast cancer." (PMID 33639614, 2021). "We also did not observe significant difference in the growth of the primary 4T1 murine mammary tumor in WT and Fstl1+/- mice, whereas more metastatic nodules were detected in the lungs of Fstl1+/− mice." (PMID 33639614, 2021). "FSTL1 is also lower expressed in the breast cancer cell line MDA-MB-231 compared to its metastatic version 231-BR." (PMID 29594389, 2018). "In contrast, a recent study focused on breast cancer showed that FSTL1 promotes bone metastasis through regulating tumor cell invasion ability and immune reprogramming." (PMID 28852126, 2017). "In the future, FSTL1 may arise as a cellular or molecular TAMs agonist or antagonist in immune checkpoint therapy of breast cancer." (PMID 37238210, 2023).
breast carcinoma (continued). "We have previously demonstrated that FSTL1 deficiency accelerates the growth of breast cancer lung metastatic tumors, but not primary tumor growth." (PMID 37238210, 2023). "Thus, the present study suggests that FSTL1 is a potential marker for predicting prognosis and a potential treatment agent for inhibiting lung metastasis in breast cancer." (PMID 37238210, 2023). "In addition, FSTL1 affects the proliferation of breast cancer cells and vascular ECs involved in angiogenesis." (PMID 36012380, 2022). "Furthermore, miR-524-5p has been studied in breast cancer to have an effect on inhibiting the follistatin-like 1 (FSTL1) gene, which is known to regulate cell proliferation, apoptosis, and metabolism." (PMID 35955787, 2022). "Similarly, FSTL1 steps up chemoresistance and sustains stemness in breast cancer cells via the integrin β3/Wnt/β-catenin pathway." (PMID 34555811, 2021). "Finally, a recent study showed that, under miR-137 regulation, FSTL1 maintained stemness in breast cancer cells via integrin b3/Wnt signaling." (PMID 34067060, 2021). "For example, FSTL1 (Follistatin Like 1) could increase breast cancer proliferation and stem cell marker expression, and it is closely associated with doxorubicin (DOX) and cisplatin (CDP) chemoresistance in breast cancer cells." (PMID 33413418, 2021). "FSTL1 (Follistatin-like protein 1) is a proinflammatory glycoprotein that has been shown to promote invasion and metastasis in colorectal cancer and chemoresistance and stemness in breast cancer." (PMID 34988553, 2021). "Transfection of lung NSCLC cell lines (PC-14 and H446), ovarian, endometrial, NPC, and breast cancer cell lines with FSTL1 reduces their growth rate via an unknown signaling pathway." (PMID 29594389, 2018). "Downregulation of FSTL1 in ccRCC and breast cancer cells promotes proliferation." (PMID 29594389, 2018). "FSTL1 is higher expressed in metastatic brain tumours compared to primary breast cancer." (PMID 29594389, 2018). "Our previous data showed that deficiency in FSTL1 could accelerate the growth of breast cancer lung metastatic tumors, but not primary tumor growth." (PMID 37238210, 2023). "However, the mechanism by which FSTL1 affects crosstalk between breast cancer cells and macrophages remains unclear." (PMID 37238210, 2023). "Therefore, FSTL1 could be potentially beneficial for the prognosis of patients with breast cancer, especially for TNBC patients." (PMID 37238210, 2023). "BMP7, GDF15, BMP5, SMAD6 and FSTL5 were highly expressed in the ER positive breast cancer cells (MCF-7 cells), while the expressions of TGFBR2, FSTL1 and NOG were reduced in this cohort." (PMID 37333824, 2023). "In this study, we analyzed the potential relationship between FSTL1 and the lungs’ TME in breast cancer metastasis." (PMID 37238210, 2023). "Furthermore, invasive breast cancer tissues sorted by luminal, HER2, and TNBC tissues showed lower FSTL1 expression than normal breast tissues." (PMID 37238210, 2023). "In our study, 4T1 breast cancer cells did not express FSTL1, and their proliferation and EMT markers did not change after treatment with recombinant FSTL1." (PMID 37238210, 2023). "Further, previous results already demonstrated that FSTL1 induced EMT in the airways of patients and mice by activating autophagy, and miR-524-5p/FSTL1 has the ability of regulating the progression of EMT of breast cancer cells." (PMID 34067060, 2021).
heart failure (19 papers, 2014 to 2025). Inability of the heart to pump blood at an adequate rate to meet tissue metabolic requirements. "Increased tissue levels of FSTL1 were associated to the severity of heart failure and to the coronary artery aneurysm formation in Kawasaki disease." (PMID 24497844, 2014). "Heterogeneity was primarily attributed to a single study that measured FSTL1 levels in heart failure patients with preserved ejection fraction." (PMID 39034719, 2024). "The concentration of circulating FSTL1 was found to be elevated in the cardiac tissue of patients with heart failure and was correlated with cardiac function during recovery." (PMID 39034719, 2024). "Prior studies have found that serum FSTL-1 levels were elevated in patients with CV diseases, including heart failure and acute coronary syndrome." (PMID 37095121, 2023). "In contrast, deletion of FSTL1 from Tie2-cre mouse endothelial/endocardium resulted in mitral valve dysfunction, heart failure, and death." (PMID 31139662, 2019). "Conditional removal of Fstl1 from the endocardial/endothelial cell lineage (Fstl1 endoKO) results in mice that die between 2 and 4 weeks after birth with heart failure with preserved ejection fraction and dysfunctional valves." (PMID 30722102, 2019). "The concentration of circulating FSTL1 increases in cardiovascular conditions such as heart failure and severe coronary artery syndrome." (PMID 31139662, 2019). "FSTL1 is a marker of remodelling also in cardiac function, where in subjects with heart failure an increase in the serum FSTL1 was observed." (PMID 28373915, 2017). "Enhanced Fstl1 expression in heart tissue and increased serum Fstl1 levels were observed in heart failure mouse models." (PMID 27799944, 2016). "This could be attributed to the measurement of FSTL1 levels in heart failure patients with preserved ejection fraction as the case group." (PMID 39034719, 2024). "There might be a synergistic effect of FSTL1 on aortic and atrioventricular valves, culminating in fibro-calcific leaflet remodeling and, ultimately, heart failure." (PMID 36684598, 2022). "However, patients with heart failure and acute coronary syndrome showed a significant increase of FSTL1 circulating concentrations." (PMID 33192583, 2020). "Furthermore, Fstl1 conditional deletion from the endocardial/endothelial lineage results in postnatal death due to heart failure and profound atrioventricular valve defects." (PMID 30722102, 2019). "Keeping this in mind, the up-regulation of cardiokine/myokine follistatin-like protein 1 (FSTL1), having been shown to be cardioprotective in heart failure, is accompanied by a reduction in cardiac ketone body uptake in a canine model of tachypacing-induced heart failure." (PMID 29928647, 2018). "Follistatin-like-1 (Fstl1) is a secreted glycoprotein expressed in the adult heart and is induced in response to injurious conditions that promote myocardial hypertrophy and heart failure." (PMID 30046617, 2018). "For instance, heart failure patients with increased Fstl1 levels in serum and the myocardium maintained the highest risk of mortality, suggesting that Fstl1 may serve as a biomarker in chronic systolic heart failure." (PMID 27799944, 2016). "The data showed that the elevated expression of FSTL1 and FSTL3 was a marker of heart failure and was detected within 30 min by synthetic Au NPs, which was accurate and rapid." (PMID 36557991, 2022). "Additionally, FSTL1 can act as an inhibitor of activins, members of the TGF-β family that contribute to the pathogenesis of heart failure." (PMID 39034719, 2024).